FAP (fibroblast activation protein alpha)
Diseases named in the same sentence as FAP in open-access papers (continued):
Sharing a sentence is not in itself a finding about the gene and the disease.
tumor (continued). "HER2-IL clearly detected both the high HER2 (SK-BR3) and low HER2-expressing (MCF-7) tumor models, as well as low FAP- (MDA-MB435S) and high FAP (HT1080-hFAP) expressing tumor models." (PMID 33076292, 2020). "FAP positive immunostaining at the tumour centre and at the infiltrating front was significantly associated with worse 5-year cancer-specific survival (CSS) of CCRCC patients." (PMID 33207686, 2020). "Serial immunofluorescence observations showed that ICOVIR15 inhibited the viability of both GFP+ tumor cells and FAP+ cells over time." (PMID 33308315, 2020). "Preclinical studies have demonstrated that CAR T cells targeted to murine FAP have anti-tumor efficacy in MPM models with minimal toxicity." (PMID 32914147, 2020). "FAP targeted vaccines have also been explored by several groups, and studies have shown that DNA vaccine targeted against FAP suppresses tumor growth in different cancer models." (PMID 32722460, 2020). "A number of groups have generated CAR-T cells targeted to mouse FAP and tested their ability to inhibit tumor growth." (PMID 32625204, 2020). "We expected this result because FAP is a marker of fibroblasts of tumour tissues with an infiltrating nature." (PMID 33207686, 2020). "Depleting FAP-expressing cells provides some tumor growth control through a process involving IFNγ and TNFα." (PMID 33050580, 2020). "CCRCC patients with tumour FAP positivity and sFAP ≤ 61.03 ng/mL had worse 5-year CSS than patients with the rest of the combinations." (PMID 33207686, 2020). "Inhibition of FAP in mice injected with the PDAC cell line Panc02 reduced the total number of the macrophages infiltrating the stroma, highlighting the importance of FAP-expressing CAFs for the macrophage abundance in the tumor stroma." (PMID 32752017, 2020). "The sensitivity of FAP at the tumour centre and at tumour front was of 53.3 and 66.7% respectively, whereas the specificity was of 76.5% and 64.9%." (PMID 33207686, 2020). "In agreement with the data obtained by IHC on the TMA, tumor samples expressed significantly higher levels of FAP compared to normal tissues (p < 2.2e-16)." (PMID 32733792, 2020). "We further investigated the localization of the Bi-FAP/mEnd-IL based fluorescence signals in freshly isolated MDA-MB231 tumor xenografts." (PMID 32316521, 2020). "Similar to the monospecific liposomes, the Bi-FAP/mEnd-IL represents a potent tool for the demarcation of invaded tumor margins and suspicious lymph nodes during intra-operative procedures." (PMID 32316521, 2020). "Together, there is substantial evidence supporting the role of FAP in tumor proliferation and metastasis." (PMID 32733792, 2020). "CD8 IHC, MHC-I IHC and FAP in situ hybridization (ISH) analyses were performed on whole slides of these tumour samples." (PMID 33149148, 2020). "Univariate analysis found tumor stages and tumor location as predictors of overall survival, whereas FAP expression showed a trend to it (p = 0.06)." (PMID 32733792, 2020). "Our results suggest that FAP plays additional roles in tumor progression such as modulation of angiogenesis and immunoregulation in the tumor microenvironment." (PMID 32733792, 2020). "Co-staining with anti-F4/80 (macrophage marker) and anti-FAP-α indicated that the majority of macrophages inside the tumor mass were likely of the tumor-permissive M2 phenotype." (PMID 33329014, 2020). "Similar results were obtained for the combination between FAP at the tumour front and sFAP (sensitivity = 41.7%; specificity = 91.2%)." (PMID 33207686, 2020). "In primary tumors, we found overall higher FAP expression at the infiltrating front with respect to the tumor center (Chi-square test p=0.1)." (PMID 32428869, 2020). "Since tumour and plasma were obtained from the same patient, we also performed Kaplan–Meier curves by combining data of tissue FAP expression and plasma sFAP levels." (PMID 33207686, 2020).
tumor (continued). "High-grade CCRCCs expressed higher percentages of FAP staining than low-grade tumours both at the centre and at the infiltrating front." (PMID 33207686, 2020). "Opposed to cell culture studies, Bi-FAP/HER2-IL-based live confocal microscopy of a high HER2-expressing tumor revealed nuclear delivery of the encapsulated dye." (PMID 33076292, 2020). "In contrast to normal stromal cells that maintain epithelial integrity and confer tumor resistance, FAP+ fibroblasts have immunosuppressive and tumor promoting properties." (PMID 33088423, 2020). "The high FAP-selectivity of UAMC1110 is particularly attractive for tumor-targeting, when taking into account the near-ubiquitous expression of the DPPs and PREP in humans." (PMID 32728930, 2020). "For example, FAP-α is selectively overexpressed by CAFs, the predominant cell type in the tumor stroma." (PMID 32775317, 2020). "Fibroblast activation protein (FAP) is a proline selective serine protease that is overexpressed in tumor stroma and in lesions of many other diseases that are characterized by tissue remodeling." (PMID 32728930, 2020). "In the case of the HT1080-hFAP, whereby the tumor cells express human FAP, the liposomes bearing FAP’scFv (Bi-FAP/mEnd-IL and FAP-IL) should also accumulate in the tumor cells." (PMID 32316521, 2020). "Because non-targeted tubulysin B was too toxic to administer at therapeutic concentrations 32, it was important to investigate the systemic toxicity of the FAP-targeted tubulysin B hydrazide conjugate at doses that displayed anti-tumor activity." (PMID 32483418, 2020). "Although the FAP-tubulysin B conjugate is solely targeted to fibroblasts, we finally demonstrate that the conjugate can completely halt tumor progression." (PMID 32483418, 2020). "Conversely, neutralizing anti-CCL2 antibody or knockdown of CCL2 remarkably blocked the migration of MDSCs and abrogated FAP(+) CAF-mediated tumor promotion." (PMID 33292459, 2020). "CAFs with especially the subtypes expressing FAP have been reported not only to physically support cancer cells but also to be key players of tumour angiogenesis." (PMID 32447444, 2020). "We further observed a stepwise increase in tumor budding according to the percentage of FAP-positive cells (p = 0.009)." (PMID 32733792, 2020). "The presence of the targets directly on the tumor vasculature guarantees a rapid detection and binding as seen with the Bi-FAP/mEnd-IL and the mEnd-IL in this tumor model." (PMID 32316521, 2020). "In general, the frequency of FAP+ tumor cells detected by flow cytometry was lower than that detected by scRNAseq, especially for specimen BT26." (PMID 33082953, 2020). "Elevated levels of activated tumor myofibroblasts are accompanied by high levels of FAP, and correlate with an invasive phenotype." (PMID 32316521, 2020). "One of the most consistent finding is that FAP promotes tumor cell proliferation, migration and invasion, all of which favor tumor growth." (PMID 32899119, 2020). "GLV-1h446, expressing anti-VEGF and anti-FAP, was specifically shown to decrease tumor proliferation in both infected and uninfected distal tumor areas, demonstrating the enhanced systemic therapeutic effects of this VV." (PMID 33167307, 2020). "In contrast, FAP was frequently detected within clusters identified as ECs, pericytes and tumor cells." (PMID 33082953, 2020). "When primary and metastatic tissues were compared, FAP expression was significantly lower in both local and distant metastases (p<0.001 in all cases) with respect to the tumor center." (PMID 32428869, 2020). "This interest is driven by the well‐established expression of FAP by stromal fibroblasts within the microenvironment of epithelial cancers, despite limited expression by the tumor cells themselves." (PMID 33082953, 2020). "In Hu-SCID tumor models, FBiTE expression in OV enhanced intratumoral accumulation of T cells and decreased the level of FAP expression in treated tumors." (PMID 32664210, 2020).
tumor (continued). "These compounds also had low nanomolar FAP-affinities, higher tumor uptakes in vivo and longer tumor retention times." (PMID 32728930, 2020). "This is seen in the fact that the monospecific FAP-IL accumulated and was activated much slower in both tumor models as compared to the Bi-FAP/HER2-IL, and revealed continuous fluorescence increases of HT1080-hFAP up to 48 h post-injection (FAP-IL)." (PMID 33076292, 2020). "IHC staining for FAP antigen in sequential tumor sections confirmed the presence of FAP within regions of the tumor, which also demonstrated increased radioactivity accumulation." (PMID 32806623, 2020). "Autoradiography demonstrated accumulated activity throughout the interior of FAP+ tumors, while sequential tumor sections stained positively for FAP expression." (PMID 32806623, 2020). "Again in FAP+ populations, disrupting pathways that mediate immunosuppression have been successful in tumor models, for example disruption of CXCL12 signaling." (PMID 32402828, 2020). "In Paulette’s research, they examined the gene expression of FAP in high-grade serous EOCs and found that a higher FAP expression in tumor tissue than normal control." (PMID 32850861, 2020). "For the lower gastrointestinal tract, in general, the main benefit of FAP-specific PET was not limited to target volume delineation but a better assessment of tumor spread and, therefore, more information to decide the oncological management of a patient." (PMID 32942573, 2020). "Vaccination against FAP expressed on CAF surfaces has also been attempted for controlling tumor growth by directly depleting the activated CAFs." (PMID 33158289, 2020). "The most consistent expression was in the EC clusters, with FAP expression in pericytes and tumor cell clusters being more variable." (PMID 33082953, 2020). "None of the three subtypes showed significant differences of FAP expression in both locations of tumours (CCRCC Chi-square test, p = 0.1; PRCC, p = 0.74; and ChRCC, p = 0.99)." (PMID 33207686, 2020). "FAP- and murine endoglin-specific single chain antibody fragments were coupled to the liposomal surface, and the liposomal potentials validated in tumor cells and mice models." (PMID 32316521, 2020). "Antibodies against FAP have confirmed the suitability of FAP as a target by demonstrating efficient tumor stroma targeting capabilities in clinical trials." (PMID 32625204, 2020). "FAP, instead, is a type II integral membrane serine protease, upregulated in epithelial carcinomas and tumor activated fibroblasts." (PMID 33585217, 2020). "Fibroblast depletion has primarily focused on the targeting of FAP-positive fibroblast populations and depletion of these fibroblasts reduces tumour ECM in lung and pancreatic cancer models." (PMID 33187209, 2020). "ICO15K-FBiTE treatment of mice bearing human lung or pancreatic tumors stimulated T cell activation and T cell infiltration into tumors, which mediated killing of FAP-positive cells, and reduced tumor growth." (PMID 33167307, 2020). "The first objective was to validate previous results and to study the heterogeneity of FAP expression in a series of 89 CCRCCs, analysing it in both the central part and the infiltrating front of primary tumours." (PMID 33207686, 2020). "In ESCC patients, the presence of FAP-positive CAFs in tumor stroma is correlated with lymph node metastasis and shorter disease-free survival." (PMID 32637576, 2020). "FAP+ cells cannot only promote tumor progression but also block immunotherapy by producing ECM and direct signaling pathways (Puré and Blomberg, 2018)." (PMID 32850861, 2020). "In fact, almost every tumor vessel was highlighted by FAP expression, whereas normal tissue vessels and cultured endothelial cells (ECs) lacked expression." (PMID 33082953, 2020). "By contrast, inhibition of FAP activity in colorectal xenograft models results in tumor growth attenuation." (PMID 32733792, 2020).
tumor (continued). "Regarding local invasion (pT), FAP expression in the tumor center gradually increased as the adenocarcinoma infiltrated the large intestine wall." (PMID 32428869, 2020). "One group reported that fibroblast activation protein (FAP)+ CAFs, one subtype of CAFs, are responsible for suppressing anti-tumor immunity and thus contribute to uncontrollable tumor growth." (PMID 33050580, 2020). "Mouse or human T cells engineered with a CAR targeting FAP improved tumor control and T cell infiltration in vivo in various mouse tumor models." (PMID 32570906, 2020). "CAFs were studied in a xenogeneic mouse model of both tumor types and characterized in terms of fibroblast activation protein (FAP), mouse PDGFR expression, metalloproteases activation, and ECM gene and protein expression profiling." (PMID 33585217, 2020). "Recently, a preclinical trial using a DNA vaccine against FAP synergized with anticancer immune therapy targeting Prostate Membrane Antigen (PMSA) in tumor-bearing mice model for prostate cancer." (PMID 31885581, 2019). "Analysis of the extracellular matrix of mouse HCC tumors revealed that Hep-55.1c tumors have distinct stroma regions composed of fibroblasts and extracellular matrix (ECM), whereas iAST tumors lack e.g. expression of FAP in the tumor microenvironment." (PMID 31291357, 2019). "We therefore aimed for further development of these FAP-targeting molecules to increase the total tumor dose while maintaining low unspecific binding to healthy tissue." (PMID 30850501, 2019). "Anti-FAP antibodies conjugated to drugs induces a cytotoxic effect, which inhibits tumor progression in gastrointestinal cancer." (PMID 31540435, 2019). "To determine the most clinically appropriate tumor type in which to study the CAF marker, fibroblast activation protein (FAP), we queried The Cancer Genome Atlas (TCGA) database for FAP expression in all available tumor types." (PMID 30726287, 2019). "The activity of FAP enzyme was investigated, because it has been reported that the accumulation of CAFs in the tumor stroma and their expression of FAP contributes to the chemoresistance to cisplatin in carcinomas." (PMID 31881770, 2019). "More recently, co-administration of a novel FAP immunogen with tumor antigen-specific DNA vaccines synergistically enhanced antitumor immunity in mouse models of lung and prostate cancer." (PMID 30927908, 2019). "On the basis of the in vitro results, 10 of the initial 15 compounds were selected for PET imaging in FAP-positive tumor–bearing mice." (PMID 30850501, 2019). "FAP has been shown to play a role in epithelial-to-mesenchymal transition (EMT) in pancreatic ductal adenocarcinomas (PDA) among other tumor types." (PMID 30804938, 2019). "Recently, oncolytic adenovirus with a FAP-targeting has displayed an improved anti-tumor immunity through endogenous T cell activation to attack FAP+ stromal cells in tumor-bearing mice models." (PMID 31462327, 2019). "As such, a contrasting result came from another study, in which adoptive transfer of FAP-reactive CAR-T cells not only had limited anti-tumor effects, but also had induced significant lethal toxicity and cachexia." (PMID 31462327, 2019). "The study reported that FAP-associated tumor invasiveness is mediated by β1-integrin and focal adhesion kinase (FAK), and that blocking FAP activity can lead to reduced invasiveness of PDAC." (PMID 31527414, 2019). "The modified SynCon FAP DNA vaccine can synergize with other tumor antigen-specific vaccine therapies in tumor-bearing mice." (PMID 31462327, 2019). "It has previously shown that these tumor models generate FAP+ stroma once implanted subcutaneosly in NSG mice." (PMID 30683154, 2019). "As an alternative immune-based targeting strategy, adoptive transfer of FAP-specific chimeric antigen receptor (CAR) T cells proved to be effective in restraining tumor growth in pre-clinical models of lung, mesothelioma and pancreatic cancer." (PMID 30927908, 2019).
tumor (continued). "The focus of this work was to enhance tumor retention of FAP-targeting radiotracers while simultaneously retaining the excellent imaging contrast of FAPI-02 and FAPI-04—that is, to develop an optimized theranostic tracer." (PMID 30850501, 2019). "The expression of OAd-infected cells specifically increased the cytotoxicity of FAP-positive target tumor cells." (PMID 30683154, 2019). "FAP showed an increased expression at the invasive part (M = 0.057, SE = 0.015) compared to the tumor center (M = 0.015, SE = 0.003; P = 0.028)." (PMID 30922247, 2019). "FAP was higher expressed at the invasive part compared to the tumor center in both stroma-high and stroma-low tumors." (PMID 30922247, 2019). "Recent data suggests FAP contributes to a suppressive tumor microenvironment via cleavage of collagen to reveal Scavenger Receptor A-2 binding sites for tumor-associated macrophages." (PMID 30726287, 2019). "Prior publications have demonstrated that tumors grown in FAP KO mice demonstrate delayed tumor growth, but enhanced disorganized collagen deposition and p21 signaling via extracellular signal–regulated kinase (ERK) and focal adhesion kinase (FAK)." (PMID 30726287, 2019). "In this case, either FAP+ CAFs depletion or inhibition of the CXCL12 receptor-CXCR4 in combination with immune-checkpoint inhibitors resulted in a clear tumor reduction." (PMID 31847096, 2019). "In this regard, a recent report described the benefits of targeting the tumor stroma with a FAP-targeting BiTE-armed vaccinia virus in an immunocompetent mouse model of cancer." (PMID 30683154, 2019). "FAP is broadly expressed in the microenvironment of a variety of tumors and thus allows targeting of different tumor entities including pancreas, breast and lung cancer, which account for a large part of the entirety of solid tumors." (PMID 31659499, 2019). "Remarkably, combining FAP vaccination with chemotherapy yielded up to 70% greater uptake of chemotherapeutic drugs in tumor xenografts." (PMID 30927908, 2019). "The expression of FAP was reduced in both tumor models, in ICO15K-FBiTE-treated tumors compared with the PBS and the control virus." (PMID 30683154, 2019). "We believe that FAP function is required for deposition and organization of extracellular matrix components, including collagen, and provides a target for improving tumor oxygenation and the quantity and function of the immune infiltrate." (PMID 30726287, 2019). "Targeting efforts against fibroblast activation protein (FAP) present another promising strategy for targeting of the microenvironment of tumours." (PMID 30823564, 2019). "Depletion of FAP+ CAFs using transgenic mice with FAP promoter- driven diphtheria toxin receptor (DTR) resulted in tumor regression in an IFNγ and TNFα dependent manner." (PMID 31428105, 2019). "Although FAP is expressed on the majority of activated fibroblasts in the tumor microenvironment, only a subset of these cells co-express αSMA." (PMID 31659499, 2019). "When treating lung cancer, a similar approach was applied to pool EphA2-targeted CAR and FAPα-targeted CAR to target the tumor microenvironment." (PMID 31754328, 2019). "We have synthetized a peptide substrate (Fmoc-Gly-Pro-Cysteic acid-Ile-Gly-NH2) in order to measure FAP activity in the plasma of naive, 4T1 tumor bearing and cisplatin treated 4T1 tumorous mice." (PMID 31881770, 2019). "In the animal models used for our experiments, genetically modified FAP-expressing tumor cells were applied, representing a rather artificial tumor model as compared with the clinical situation." (PMID 30850501, 2019). "Altogether, these results indicate that the T cells retargeted by the FBiTE are responsible for killing the FAP-positive murine CAFs in the tumor mass." (PMID 30683154, 2019). "FAP+ CAFs inhibit the anti-tumor effect of M-CSF blockade by upregulating the infiltration of polymorphonuclear MDSCs in the TME." (PMID 31462327, 2019).